BIRC5 (baculoviral IAP repeat containing 5)
Diseases named in the same sentence as BIRC5 in open-access papers (continued):
Sharing a sentence is not in itself a finding about the gene and the disease.
tumor (continued). "Although it has been confirmed that BIRC5 can affect the occurrence and development of tumors by affecting the tumor microenvironment in a variety of tumors, it is still a lack of literature to report whether BIRC5 also affects the development of PCa by affecting the tumor microenvironment." (PMID 37077837, 2023). "Furthermore, the compound inhibits tumor cells proliferation in the athymic xenograft mice model, without any apparent toxicity yet suppressing the expression of Wnt target genes associated with tumor growth, including MYC (c-myc), CCND1 (cyclin D1), and BIRC5 (survivin)." (PMID 35053565, 2022). "Therefore, we selected circCAMSAP1 as our gene of interest, and through bioinformatics analysis, we hypothesized that tumor progression could be influenced by the circCAMSAP1/miR-1182/BIRC5 axis." (PMID 35132928, 2022). "Here, the authors used single cell sequencing to study the tumours of patients that were responsive and resistant to treatment and find gains of 17q in resistant tumours, which they attribute to increased expression of Birc5 and validate these findings in mouse models of the disease." (PMID 34001881, 2021). "Furthermore, TPX2, ZWINT, UBE2C, CCNB2, CDK1, BUB1, and BIRC5 may orchestrate the stemness, proliferation, and invasion of tumor cells." (PMID 34671679, 2021). "The relationship between BIRC5 expression levels and the clinicopathological characteristics of patients with different tumors was analyzed based on stage pathology grade, tumor mutation burden (TMB), and microsatellite instability (MSI) status of tumor samples from the TCGA database." (PMID 33431968, 2021). "Therefore, BIRC5 may also regulate tumor cell biological process, thus affecting the prognosis of chRCC via CD4+ T cells." (PMID 32662515, 2020). "Previous studies revealed that BIRC5 could promote tumor cell proliferation in RCC." (PMID 32662515, 2020). "For replicative conditioning, the fragment representing the Survivin/BIRC5 promoter was identified and proven to recapitulate the optimal expression features of the reference cellular gene in terms of transcription strength, tumour selectivity and cell cycle regulation." (PMID 32152425, 2020). "Thus, the SPR immunosensor based detection of BIRC5 protein in sera may serve as a prognostic biomarker if it is conclusively proved that BIRC5 protein starts appearing in serum before the tumour mass is apparently visible." (PMID 31530877, 2019). "However, to confirm its utility for early diagnosis and prognosis, systematic study in experimentally induced CMT in dogs need to be taken up for monitoring serum BIRC5 levels, before onset of tumour, during tumour progression and after surgical removal of tumour mass or chemotherapy." (PMID 31530877, 2019). "BIRC5 is often highly expressed in malignant cells but not in differentiated tissues, and high expression levels are associated with poor prognosis thus appointing it an attractive target in tumour therapy." (PMID 28791312, 2017). "Additionally, BIRC5 overexpression attenuated the repressive effect of miR-138-5p on tumor growth, suggesting that miR-138-5p might inhibit tumor growth by silencing Survivin." (PMID 27978829, 2016). "Therefore, the identification of BIRC5 as a miR-203 target gene may explain, at least in part, the molecular mechanism of tumor suppression by miR-203." (PMID 22713668, 2012). "In in vivo experiments, tumours in nude mice treated with JPJDXZF exhibited reduced volume and weight, along with decreased expression of BIRC5 and Hippo pathway effectors YAP and TAZ." (PMID 41795151, 2026).
tumor (continued). "The epitopes are derived from four TAAs that are either over-expressed (BCAN, BIRC5, PTPRZ1) or where the epitope is over-presented (NLGNX4) in a large proportion of GBM tumours compared with most healthy tissues." (PMID 41051649, 2025). "Survivin(BIRC5), an inhibitor of apoptosis (IAP) protein, is overexpressedin TNBC and contributes to tumor progression, chemoresistance, andpoor prognosis." (PMID 41342191, 2025). "Immunohistochemical database analysis reveals that EIF4EBP1, RIMKLA, and BIRC5 are highly expressed in tumour tissues, while the PCK1, PLG, PEBP1, and CAT show a lower expression in tumour samples." (PMID 40591061, 2025). "For example, the elevated expression of MX2 and BIRC5 in CD8+ T cells indicates their potential to enhance T cell-mediated cytotoxicity, which is crucial for anti-tumor immunity." (PMID 40243888, 2025). "CDKN2A, BIRC5, and SPP1 expression levels were significantly upregulated in tumor tissues (p < 0.001), while IGF1 expression was considerably downregulated (p < 0.001)." (PMID 39042294, 2024). "Additinally, the knockdown of KLF4 in the SW480 CRC cell line induced the YAP pathway and its downstream genes, including EGFR, MYC, BIRC5, and CTGF, leading to tumor proliferation." (PMID 38167453, 2024). "Compared with those in adjacent tissues, the expression levels of CDKN2A, BIRC5, and SPP1 were significantly upregulated in tumor tissues (p < 0.05), while the expression of IGF1 was considerably downregulated (p < 0.001)." (PMID 39042294, 2024). "To start, we contrasted the immunohistochemical staining of BIRC5 (classical oncogene) and PSMB10 in primary tumor tissues and normal tissues in cases of KIRC." (PMID 38794205, 2024). "TBX5 and YES-associated protein 1 (YAP1) form a complex with β-catenin, which localizes and activates BCL2 Like 1 (BCL2L1) and Baculoviral IAP Repeat Containing 5 (BIRC5), thereby enhancing the anti-apoptotic effect on tumor cells." (PMID 38965548, 2024). "Our findings demonstrated the anti-tumor effect and epigenetic mechanism of YM155, a BIRC5 inhibitor, through in vitro and in vivo experiments." (PMID 38203388, 2023). "We then analyzed the mRNA expression of the eight members of the BIRC family and found that only BIRC5 and BIRC7 were overexpressed in tumor tissues." (PMID 38203388, 2023). "In HCC tumor tissue samples, CD11b was used to indicate MDSC infiltration level, and a positive correlation between CD11b and Birc5 staining was observed." (PMID 37326143, 2023). "In the clinical group Tumor status: Tumor free and with tumor, the genes TOP2A, BIRC5, VEGFA had highly statistical significance, while the genes HIF1A, ACSL3, FTH1 didn’t have statistical significance." (PMID 37248280, 2023). "Of note, the results revealed that BIRC5, BUB1, and TPX2 were positively correlated with tumor purity, whereas GNG7 and SST were negatively correlated with tumor purity." (PMID 36863706, 2023). "Highly expressed E2F3 in NPC cells activates transcription of PRC1 and BIRC5, which renders an immunosuppressive TME characterized by abundant M2 TAMs to trigger the growth and metastasis of tumor cells." (PMID 37647439, 2023). "The results indicated that NAIP, BIRC2, BIRC3, XIAP, BIRC5, and BIRC6 showed significantly higher expression levels in tumor tissues than in normal tissues." (PMID 37781078, 2023). "Higher BIRC5 levels were correlated with higher BCLC stage, tumor grade and with higher observed BIRC5 levels in metastatic sites in patients who died after 3 years of disease." (PMID 37744383, 2023). "Even though there are some differences between our patients and the TCGA cohort patients, BIRC5 and SKP2 were still both overexpressed in HCC tissues compared with tumor-adjacent tissues in our TMA cohort." (PMID 37679418, 2023). "The results revealed that AURKA, BIRC5, CCNB1, CDK1, CDKN3 and TYMS were significantly upregulated in tumor tissues." (PMID 37393234, 2023).
tumor (continued). "Previously, we and others have reported that Hippo/YAP1 mediates CSC attributes and tumor progression through regulation of its downstream targets, such as SOX9, Birc5, and Cyr61." (PMID 35996148, 2022). "Since high levels of HIF-1α are strongly correlated with the expression of survivin, a protein involved in tumor progression, we analyzed the transcript levels of the corresponding gene Baculoviral IAP Repeat-Containing Protein 5 (BIRC5)." (PMID 36142158, 2022). "BIRC5, an ATG12-ATG5 conjugate interactor has also been found to be expressed predominantly by tumor cells." (PMID 35884522, 2022). "The TAA/ABL1 mRNA ratios in the tumor cell line-spiked samples were highly reproducible, with a CV of 0.05 and 0.11 for WT1/ABL1, 0.1 and 0.21 for PRAME/ABL1, and 0.12 and 0.21 for BIRC5/ABL1." (PMID 36248870, 2022). "BIRC5 is positively regulated by the AKT/mTOR pathway to inhibit autophagy and apoptosis and promote tumor cell survival." (PMID 36713522, 2022). "BIRC5 belongs to the inhibitor of apoptosis protein (IAP) family and is highly expressed in various tumor tissues." (PMID 35132928, 2022). "FBXL7 gene functions are poorly understood, but the gene’s role as a tumor suppressor has been proposed based on its target proteins, AURKA, BIRC5 and c-SRC." (PMID 35887149, 2022). "Baculoviral IAP Repeat Containing 5 (BIRC5) is well studied in many malignancies, its prognosis value and correlation with the tumor microenvironment (TME) in LAUD remains largely elusive." (PMID 36046648, 2022). "The expression profiles of genes in the first cluster across all tumours (TOP2A, CDK1, BIRC5, GPC3, IGF2 and AFP) were strongly correlated." (PMID 36345011, 2022). "Firstly, we found that BIRC5 methylation was lower in LGG than in healthy brain tissue and was negatively correlated with tumor grade in LGG." (PMID 35309512, 2022). "Through a screening in TCGA-KIRC database, we compared the expression levels of CANX, MAPK1, BIRC5, NAMPT, and BID in normal kidney tissues and renal clear cell tumor tissues, and we found that their expression levels in tumor tissues were upregulated." (PMID 34988121, 2021). "We observed that the BIRC2, BIRC3, BIRC5, and BIRC7 genes showed the increased levels of expression in tumor tissue compared to normal tissue, while in the case of the BIRC1, BIRC4, BIRC6, and BIRC8 genes, we saw the decreased expression levels." (PMID 33673050, 2021). "Experimental investigation showed that BIRC5 can promote the expression of VEGF, which in turn promotes angiogenesis in the tumour stromal." (PMID 33962640, 2021). "We found that the expression levels of CANX, BIRC5, BID, and NAMPT in tumor tissues were significantly higher than their expression levels in normal tissues, indicating that they are all significantly related to tumor occurrence and development." (PMID 34988121, 2021). "Analysis of clinical samples validated the overexpression of the 4 genes (SQSTM1, BIRC5, NRG3, and CXCR4) in tumor tissues relative to paired normal tissues, consistent with bioinformatic findings." (PMID 34484469, 2021). "BIRC5 and HK2 showed higher expression in MYCN amplified cell lines and tumor tissues consistently, whereas GRID2 and RNASEL showed the opposite trends." (PMID 34746127, 2021). "CTL activity and tumor growth inhibition was significantly enhanced in vivo in mice vaccinated with a combination of MUC1 and BIRC5 tumor gene vaccine." (PMID 33431968, 2021). "Downregulation of BIRC5 (survivin), which is the top-ranked biomarker revealed by CGM, was reported as an inhibitor of tumour cell migration and invasion through the PI3K/Akt signalling pathway." (PMID 34131308, 2021).
tumor (continued). "TIMER tool further revealed expression of the 5 signature genes (ZNF695, CENPA, TROAP, BIRC5 and KIF20A) was strongly and positively correlated with high tumor purity but negatively influenced the infiltration of CD8+ T cells and macrophages." (PMID 33995639, 2021). "It was found that CSCs specifically expressed BIRC5, PTTG1, CENPF and CDKN3 genes and presented a scattering distribution in the bulk tumor tissues, which further verified the relatively rare characteristics of CSCs." (PMID 33162821, 2020). "Compared to the NCI60 analysis, we further revealed distinct expression pattern of BIRC5 and BIRC7 and synchronized expression for NAIP, BIRC2, BIRC3, XIAP and BIRC6 in multiple tumor types." (PMID 31964418, 2020). "This was confirmed by RNAscope analysis performed on three out of six genes (BIRC5, CDK1, and PBK), showing their predominant expression on tumor cells of NB patients." (PMID 33239635, 2020). "Previous studies have confirmed that MCM2, BIRC5, and RFC4 are abnormally highly expressed in HCC, and that they participate in the regulation of HCC tumor biology." (PMID 31534853, 2019). "Some of the selected genes by CARS scores with α1 = 0.1 match previous results from the literature: according to the NCBI database, the “BIRC5 baculoviral IAP repeat containing 5” is an inhibitor of apoptosis and found in most tumor cells." (PMID 30793795, 2019). "circFAT1 knockdown reduced the mean area immunopositive for YAP1, c-Myc, and Birc5 in tumor tissues, as determined by immunohistochemistry, this corresponded to a decrease in the levels of YAP1, c-Myc, and Birc5 protein and mRNA." (PMID 30514309, 2018). "The multivariate analysis of this data revealed that BIRC5 mRNA expression is an independent prognostic factor in OSCC and correlates with tumor stage." (PMID 30205554, 2018). "The tumor suppressor gene CDKN1A was one of the most upregulated while oncogenic cell cycle genes such as WDHD1 and BIRC5 were among the downregulated genes." (PMID 30543688, 2018). "BIRC5, FOXO1 and SQSTM1 protein expression level were detected by immunohistochemistry (IHC) in 302 HCC tissues and in 41 non-tumor tissues." (PMID 29707114, 2018). "Accordingly, we expected that qRT-PCR detection of the tumor markers TERT and Survivin/BIRC5 would contribute to a sensitive assay of immortalized RPE cells." (PMID 28811571, 2017). "mRNA and protein analyses confirmed that YM155 downregulated the tumour promoters BIRC5 and ID1 and upregulated the tumour suppressors FOXO1 and CYLD." (PMID 28582447, 2017). "The gene profiles indicated that YM155 down-regulated ID1 and BIRC5 which are tumour promoters, and upregulated CYLD and FOXO1 which are tumour suppressors." (PMID 28582447, 2017). "The muscle invasive tumour, however, showed a basal subtype (higher expression of CDH3, CD44, KRT5 and KRT6A) and likewise high aggressiveness (higher expression of KPNA2, BIRC5, CDC25B, COL4A1, and MSN)." (PMID 28916750, 2017). "BIRC5, the target of Wnt pathway, is also highly expressed in LIHC tumours and is suppressed by effective compounds in LIHC." (PMID 28699633, 2017). "In this particular case, MYC overexpressing tumour cells appear to be reliant upon the activity of the inhibitor of apoptosis protein (IAP), BIRC5 (survivin) a CDK1 target." (PMID 26881434, 2016). "The results are also consistent with reduced expression of the antiapoptotic genes Birc3, Birc5 and Nos2 in livers from TLR4-/- mice suggesting that TLR4 mediates survival ligands to tumor initiating cells." (PMID 27391331, 2016). "The expression levels of BIRC5, TK1, TNNT1 and MMP9 were found to be positively related to tumor recurrence after cystic resection." (PMID 25970782, 2015).
tumor (continued). "Relative expression levels of the eight genes of interest (AZGP1, BIRC5, DHCR7, IL6ST, MGP, RBBP8, STC2, and UBE2C) were compared between paired whole tissue sections and tumor-enriched specimens." (PMID 25218890, 2014). "In the in vivo experiments, BIRC5-shRNA expression inhibited the growth of HCC xenograft tumors by inducing cell apoptosis, although tumor growth was restored in the late stage after the adenovirus injections ceased." (PMID 23433354, 2013). "In fact, a large subset of patients classified with very favorable outcome shared a common molecular tumor phenotype characterized by ER-positive and/or ERBB2-negative status and low proliferation (low levels of E2F1 as well as BIRC5,TYMS,TOP2A and TK1)." (PMID 17535433, 2007). "From tumor immunophenotype analysis we interpreted that higher correlation of CDKN2 A and MUC5B to step 1, BIRC5 to step 2 while CCR9 to step 6 which means their up-regulation is associated with increased antigen recognition, antigen presentation and T cell activation." (PMID 40653567, 2025). "Prognostic genes including EZH2, PCNA, and BIRC5 were specifically expressed in epithelial clusters, while CHMP4C, ATP13A2, and ALDOA showed broader expression patterns, supporting their tumor-specific roles." (PMID 40678068, 2025). "Additionally, these cells exhibit specific upregulation of CEP55, PBK, BIRC5, STMN1, MT2 A, and CKS1B, all of which are related to tumor inflammatory responses." (PMID 40524208, 2025). "Firstly, this investigation did not encompass benign liver diseases and other tumor types, thus failing to further evaluate the specificity of anti-BIRC5 autoantibody for diagnosing HCC." (PMID 38832035, 2024). "Histologically, tumor proliferation, apoptosis and angiogenesis were not altered by the decreased survivin levels in the NB of Birc5+/-/MYCNtg/+ mice." (PMID 38136322, 2023). "BIRC5 is abundantly expressed in fetal tissues and various human malignant tumour tissues, but not in normal tissues or well‐differentiated adult tissues." (PMID 37340587, 2023). "Besides, it is important to consider the contributions of BIRC5 and SKP2 to the tumor microenvironment." (PMID 37679418, 2023). "Notably, we found substantial connections between the expression of BIRC5, E2F1, SFN, and UBE2C and the pathological stage of HCC, indicating their potential as indicators of tumor progression and severity." (PMID 38283837, 2023). "This study showed that BIRC5, SLCO4A1, POPDC3, and HK2 were significantly downregulated in stage MS NB and affected the survival rate of children, indicating that the low expression of these four genes is a factor conducive to tumor regression." (PMID 36713522, 2022). "Sig27var25 and SigIQvar8 are highly effective at predicting ACC prognosis and progression; both signatures contain component genes predicting poor OS independently of age and tumor stages, for instance SNHG10 and RECQL4 for SigIQvar8 as well as MXD3, BIRC5, and RAB30 for Sig27var25." (PMID 35681785, 2022). "Interestingly, we found a co-overexpression of KDM5C and the tumor prognostic genes HIF1A, p75 and survivin (alias BIRC5), involved in hypoxia-mediated mechanisms, as aggressiveness and a poor therapeutic response." (PMID 36142158, 2022). "Unfortunately, BIRC5 expression was not related to tumor purity or infiltrating levels of immune cells." (PMID 35693556, 2022). "Furthermore, in vivo study suggested elevated tumor weight and PD-L1 levels in xenograft tumors generated from LLC cells with overexpressed BIRC5." (PMID 36046648, 2022).